ARX (aristaless related homeobox)
Description:
DNA-binding transcription factor that plays a central role in the differentiation and development of type A pancreatic cells, which are located in the islets of Langerhans and secrete glucagon (By similarity). Binds to specific sequence motif 5'-TAATTA-3' in regulatory elements of target genes. Also plays a key role in intestinal enteroendocrine cell differentiation by promoting differentiation of intestinal enteroendocrine cell types L, -N, -D, -I and -G. Required for normal brain development: plays a role in neuronal proliferation, interneuronal migration and differentiation in the embryonic forebrain. May also be involved in axonal guidance in the floor plate (By similarity). Promotes expression of transcription of KDM5C. Activates expression of KDM5C synergistically with histone lysine demethylase PHF8 and perhaps in competition with transcription regulator ZNF711; synergy may be related to enrichment of histone H3K4me3 in regulatory elements.
Synonyms: ISSX; CT121; EIEE1; MRX29; MRX32; MRX33; MRX36; MRX38; MRX43; MRX54; MRX76; MRX87; MRXS1; PRTS
Tractability: PROTAC: its protein half-life has been measured.
Gene: Protein-coding gene on chromosome X (25,003,694 to 25,016,420, reverse strand). Ensembl gene ENSG00000004848.
Subcellular location: Nucleus; Chromosome
Gene Ontology:
Molecular function: DNA-binding transcription activator activity, RNA polymerase II-specific; DNA-binding transcription factor activity, RNA polymerase II-specific; DNA-binding transcription repressor activity, RNA polymerase II-specific; protein binding; RNA polymerase II cis-regulatory region sequence-specific DNA binding; sequence-specific double-stranded DNA binding; RNA polymerase II transcription regulatory region sequence-specific DNA binding; chromatin binding; DNA binding
Biological process: negative regulation of transcription by RNA polymerase II; positive regulation of transcription by RNA polymerase II; neuron development; pancreatic A cell differentiation; regulation of transcription by RNA polymerase II; enteroendocrine cell differentiation; neuron differentiation; regulation of DNA-templated transcription
Cellular component: chromatin; nucleus; chromosome
Gene-disease validity (ClinGen):
ClinGen rates the evidence that ARX causes each of these diseases.
genetic developmental and epileptic encephalopathy (X-linked): Definitive. A complex neurodevelopmental disorder characterized by a range of developmental delays and epileptic encephalopathy phenotypes.
X-linked complex neurodevelopmental disorder (X-linked): Definitive. A complex neurodevelopmental disorder that is transmitted via X-linked inheritance, and is characterized by intellectual disability, autism and epilepsy.
Homologues: Orthologues: macaque ARX (99% identical), pig ARX (97% identical), rat Arx (96% identical), mouse Arx (96% identical), chimpanzee ARX (95% identical), dog ARX (90% identical), rabbit ARX (71% identical), tropical clawed frog arx (68% identical), guinea pig ARX (56% identical), zebrafish arxa (56% identical), zebrafish arxb (37% identical). Paralogues in human: ALX4 (20% identical), RAX (19% identical), SHOX2 (19% identical), VSX2 (18% identical), SHOX (17% identical), OTP (17% identical), UNCX (17% identical), PAX7 (17% identical), EVX2 (16% identical), ALX1 (16% identical), PITX1 (16% identical), PITX3 (16% identical), and 38 more.
Diseases named in the same sentence as ARX in open-access papers:
ARX is named in the same sentence as 94 diseases in open-access papers, as found by Europe PMC text mining. Sharing a sentence is not in itself a finding about the gene and the disease. The quoted sentences say what the papers report.
epilepsy (35 papers, 2009 to 2025). A brain disorder characterized by episodes of abnormally increased neuronal discharge resulting in transient episodes of sensory or motor neurological dysfunction, or psychic dysfunction. "To test how these variants impact DNA cooperativity, we performed comparative EMSAs with ARX wildtype (R44) and the ARX R44Q variant associated with intellectual disability and epilepsy." (PMID 41279221, 2025). "For example, variants in ARX have been associated with epilepsy, lissencephaly, intellectual disability, corpus collosum abnormalities, and autism." (PMID 41279221, 2025). "Developmental and epileptic encephalopathy type 1 (DEE1) is a rare drug‐resistant pediatric epilepsy caused by trinucleotide repeat expansions in the X‐linked ARX gene, leading to elongation of the first polyalanine tract." (PMID 40608247, 2025). "In this report, we present three patients with severe movement disorders as part of ARX‐associated epilepsy‐dyskinesia syndrome, including a patient with a novel pathogenic missense variant (p.R371G)." (PMID 38711225, 2024). "Epilepsy in patients with the ARX gene variants was associated with GABAergic function abnormalities and impairment in forebrain cerebral cortical interneuron function." (PMID 36845779, 2023). "For instance, loss of function variants in the transcription factor ARX are associated with a myriad of X-chromosome linked epilepsies." (PMID 29962935, 2018). "Mutations in ARX result in a broad range of neurologic phenotypes from severe structural anomalies of the brain with accompanying epilepsy and intellectual disabilities, to structurally normal brains having similar intellectual disabilities and epilepsy." (PMID 28103279, 2017). "All patients with ARX mutations have some degree of intellectual disability, and almost all develop epilepsy during early childhood." (PMID 27287386, 2016). "In a similar fashion, mutations in the ARX gene are associated with a variety of neurological syndromes that combine epilepsy and various degrees of cognitive disabilities." (PMID 21876820, 2011). "Both genes also regulate Arx, a homeobox transcription factor required for the migration of interneurons, whose human equivalent ARX, when mutated, is associated with X-linked MR and epilepsy." (PMID 19557186, 2009). "The aristaless-related homeobox (Arx) transcription factor, located on the X chromosome, has been implicated in a wide range of neurological disorders, including intellectual disability and epilepsy, as well as diabetes and pancreatic developmental disorders." (PMID 40226590, 2025). "Futhermore, the aristaless-related homeobox (Arx) transcription factor, located on the X chromosome, has been implicated in a wide range of neurological disorders, including intellectual disability and epilepsy, as well as ASD." (PMID 41210134, 2025). "Moreover, ARX mutations contribute to defective interneuron differentiation and impaired GABAergic signaling within the hippocampus, strongly correlating with epilepsy phenotypes." (PMID 41300237, 2025). "For instance, a regulatory pathway associated with X-linked ID and epilepsy links KDM5C to polyalanine expansions in ARX, suggesting that the length of polyalanine tracts may correlate with the severity of X-linked ID and/or epilepsy." (PMID 39408661, 2024). "In humans and mice, the Aristaless Related Homeobox (ARX) gene has a polyalanine expansion mutation that is known to cause intellectual disability, epilepsy, and brain malformations and has a similar spatial expression profile as RAPGEF5 determined by in situ hybridization." (PMID 39342265, 2024). "ARX mutations have been identified as associated with a variety of genetic diseases (X‐linked mental retardation), malformations of cortical development and epilepsy." (PMID 36065764, 2022). "Mutations in ARX gene should be considered in patients with mental disability or/and epilepsy." (PMID 28174645, 2017).
epilepsy (continued). "Interestingly, ARX is an another epilepsy-related gene encoding a transcription factor which regulates LGI1 expression." (PMID 26878798, 2016). "This supports the hypothesis that even if ARX mutations might have broader consequences for cortical development, the specific effect on IN migration is fundamental to the development of epilepsy." (PMID 21876820, 2011). "To date, more than 100 male patients with pathologic loss-of-function (LoF) variants in the ARX gene have been reported, and the associated phenotype is characterized by constant intellectual disability (ID) that can be associated with neuronal migration defects and severe epilepsy." (PMID 39408661, 2024). "Collectively, these results suggest impaired cortical excitatory cell development may be impaired with CHD2 and ARX loss, both genes implicated in early onset epilepsies, though further studies are required to understand the putative pathogenic role in development of seizures." (PMID 29962935, 2018). "In the context of developmental malformations, ARX related syndromes can be thus considered as “inter-neuronopathies” and the epilepsy and ID would be directly related to the reduction of inhibition." (PMID 38612920, 2024). "Mutations in the Aristaless Related Homeobox (ARX) gene are associated with a spectrum of structural (lissencephaly) and functional (epilepsy and intellectual disabilities) neurodevelopmental disorders." (PMID 28103279, 2017). "A multigene epilepsy panel identified a hemizygous de novo missense variant in the homeodomain of ARX (NM_139058.3: c.1111C >G, p.R371G) which, although not reported previously, results in a likely damaging change in the homeodomain." (PMID 38711225, 2024). "Intractable epilepsy has been reported in patients with ARX gene variants." (PMID 36845779, 2023). "In addition, CNVs covering the regulatory elements of the ARX gene might cause an intellectual disability phenotype, and rare non-coding CNVs near previously known epilepsy genes were enriched in a cohort of 198 individuals affected with epilepsy compared to controls." (PMID 31417368, 2019). "ARX mutations cause intellectual disability with or without additional features including epilepsy, infantile spasms, dystonia, lissencephaly, autism and dysarthia." (PMID 20148114, 2010). "Nonsense mutations, polyalanine tract expansions and missense mutations in ARX cause a range of intellectual disability and epilepsy phenotypes with or without additional features including hand dystonia, lissencephaly, autism or dysarthria." (PMID 20148114, 2010). "Among the triplosensitive genes located in the duplicated region, ARX, CDKL5, CNKSR2, MID1, PTCHD1, RPS6KA3, and SMS are known to be involved in intellectual developmental disorders with/without epilepsy." (PMID 39062680, 2024).
Intellectual disability (27 papers, 2007 to 2025). "Variants in the Aristaless‐related homeobox (ARX) gene lead to a variety of phenotypes, with intellectual disability being a steady feature." (PMID 38400608, 2024). "Variants in Aristaless‐related homeobox (ARX) gene lead to a variety of phenotypes with intellectual disability being a steady feature." (PMID 38400608, 2024). "Mutations in ARX cause a broad variety of neurologic symptoms, ranging from severe brain malformation to structurally normal brains having intellectual disabilities and epilepsy." (PMID 32257294, 2020). "In humans, mutations of ARX result in mental retardation and interneuronopathies, as well as in agenesis of the corpus callosum, a condition entailing deficits in problem solving and social skills that often fall within the autistic spectrum." (PMID 29922639, 2018). "Laperuta and colleagues reported marked intra-familial clinical variability in five male relatives with X-linked mental retardation due to ARX duplication." (PMID 26522270, 2015). "In the absence of a pathognomonic clinical feature, we propose that molecular analysis of the ARX gene should be included in routine diagnostic practice in individuals with either nonsyndromic or syndromic intellectual disability." (PMID 26029707, 2015). "The Aristaless-related homeobox (ARX) gene is implicated in intellectual disability with the most frequent pathogenic mutations leading to expansions of the first two polyalanine tracts." (PMID 26029707, 2015). "Overall, these results identified multiple new candidate targets for Arx and should help to better understand the pathophysiological mechanisms of intellectual disability and epilepsy associated with ARX mutations." (PMID 21966449, 2011). "We have identified two novel point mutations in the R379 residue of the ARX homeodomain; c.1135C>A, p.R379S in a patient with infantile spasms and intellectual disability and c.1136G>T, p.R379L in a patient with XLAG." (PMID 20148114, 2010). "In conclusion, the identification of a new MRX family linked to Xp22 and carrying the c.428_451dup24 (ARXdup24) underlines the high contribution of ARX to X linked mental retardation." (PMID 17480217, 2007). "In humans, mutations in ARX lead to intellectual disability." (PMID 41459558, 2025). "The main feature of the mutation phenotype in ARX is intellectual disability." (PMID 38400608, 2024). "Patients with ARX gene variants suffer intellectual disability and early-life epilepsy." (PMID 36733270, 2022). "Patients harboring a mutation in ARX present with a spectrum of neurological disorders ranging in severity from lissencephaly with ambiguous genitalia (XLAG syndrome) to those with isolated intellectual disabilities (ID)." (PMID 27287386, 2016). "Five cases presented a probably non-pathogenic variant, including the novel HGVS: c.441_455del, classified as unlikely disease causing, consistent with reports that suggest that in frame deletions in polyalanine stretches of ARX rarely cause intellectual disability." (PMID 26029707, 2015). "The ARX mutations encompass a nearly continuous spectrum of neurodevelopmental disorders (NDDs), ranging from lissencephaly to Proud syndrome, as well as infantile spasms without brain malformations, and including both syndromic and non-syndromic intellectual disabilities (IDs)." (PMID 39408661, 2024). "Global developmental delay or intellectual disability is frequently found in patients with ARX variants, including in our patient." (PMID 36845779, 2023). "His X-linked intellectual disability panel was notable for four potential disease-causing variants (in each of ATRX, FANCB, ZNF81, and ARX), but all were of undetermined significance." (PMID 34575122, 2021).
Intellectual disability (continued). "Hence, identifying the subpopulations of interneurons that persist and how they function remains an important question that may help in understanding not only the pathobiology underlying ARX mutations, but also potentially other forms of developmental epilepsies with intellectual disabilities." (PMID 27287386, 2016). "Patients with mutations in ARX present with intellectual disability and epilepsy, with or without structural defects in the brain such as lissencephaly (smooth brain), microcephaly (small brain), and agenesis of the corpus callosum, as well as abnormal genitalia." (PMID 30659230, 2019). "The c.429_452dup24 mutation of the ARX gene constitutes a recognizable clinical syndrome: ARX patients exhibiting Intellectual Deficiency with no primary motor impairment, but with a very specific upper limb distal motor apraxia associated with a pathognomonic hand-grip." (PMID 24528893, 2014). "In conclusion, laboratories performing molecular genetic studies of idiopathic intellectual disability would benefit from the implementation of this methodology, which enables a widened scope of detection of the mutational hotspot regions of FMR1, AFF2 and ARX genes in a single initial assay." (PMID 23914978, 2013).
Lissencephaly (21 papers, 2010 to 2025). A spectrum of malformations of cortical development caused by insufficient neuronal migration that subsumes the terms agyria, pachygyria and subcortical band heterotopia. "MRI findings usually found in patients with an ARX variant were lissencephaly, agyria or pachygyria and agenesis of the corpus callosum." (PMID 36845779, 2023). "Variants in the ARX gene are characterized by abnormalities such as microcephaly and lissencephaly, plus ACC." (PMID 31231230, 2019). "One potential cause for agenesis appeared in the context of lissencephaly form XLAG (X-linked lissencephaly with abnormal genitalia) in terms of mutations in the gene Aristaless-related homeobox (ARX)." (PMID 31010135, 2019). "The genetic factors known to cause lissencephaly are DCX (double cortin), gene TUBA1A (tubulin alpha 1a), ACTB (actin beta), ACTG1 (actin gamma 1), and ARX (aristaless-related homeobox)." (PMID 39040723, 2024). "X-linked lissencephaly with ACC and ambiguous genitalia is caused by variants in the ARX gene and affects primarily males." (PMID 35743840, 2022). "Interestingly, a number of missense mutations across this C-terminal portion of the ARX gene including the Aristaless domain lead to Early Infantile Epileptic Encephalopathy (MIM#308350) or in one case the severe brain malformation phenotype of lissencephaly, X-linked 2 (MIM#300215)." (PMID 30419043, 2018). "This pattern also significantly differs from foetal ARX related lissencephaly, where the cortical plate is mainly three-layered and contains exclusively pyramidal neurons with an absence of interneurons." (PMID 25059107, 2014). "Given the involvement of mutations in TUBA1A in phenotypes with lissencephaly and other similar clinical findings to the severe XLAG phenotype due to mutations in ARX we wanted to investigate the novel interaction between ARX and TUBA1A further." (PMID 20148114, 2010). "An increase in ARX gene dosage results in a range of disorders, including developmental and epileptic encephalopathy, intellectual developmental disorder, lissencephaly, Partington syndrome, Proud syndrome, and hydranencephaly with abnormal genitalia, such as cryptorchidism and hypospadias." (PMID 39062680, 2024). "A further patient with 46,XY partial GD had lissencephaly with absence of corpus callosum, intractable seizures, and choroid coloboma suggesting the aristaless-related homeobox (ARX) gene mutation." (PMID 28825592, 2018). "MRI demonstrates a wide spectrum of brain dysgenesis ranging from simplified gyral pattern to agyria, resembling the classical lissencephaly but in combination with specific features which are not observed in ARX, LIS1, DCX, or RELN mutations." (PMID 25059107, 2014). "In lissencephaly with an anterior to posterior gradient and severe cerebellar hypoplasia, mutations of RELN, CDK5, or VLDLR should be suspected, whereas a posterior to anterior gradient with agenesis of the corpus callosum is indicative of ARX or TUBA1A mutations." (PMID 35743840, 2022).